BRAF (B-Raf proto-oncogene, serine/threonine kinase)
Diseases named in the same sentence as BRAF in open-access papers (continued):
Sharing a sentence is not in itself a finding about the gene and the disease.
cutaneous melanoma (continued). "We identified 46 patients (21 female, 25 male) diagnosed with cutaneous melanoma who underwent BRAF mutation testing from liquid biopsy." (PMID 35159044, 2022). "BRAF serine/threonine kinase (BRAF) is a cellular regulator of proliferation and survival that is mutated in more than 60% of cutaneous melanomas." (PMID 35954441, 2022). "BRAF is the top mutated gene in the skin cutaneous melanoma (SKCM) and papillary thyroid carcinoma (THCA/PTC) cohorts in both countries." (PMID 36163440, 2022). "For patients harboring a BRAF-mutation, approximately 50 to 60% of patients with cutaneous melanoma, BRAF/MEK-inhibitors are also available." (PMID 35247992, 2022). "In acral melanoma, BRAF mutation was observed in 2 (13.3%, 2/15) patients, which was significantly lower than that in cutaneous melanoma (p = 0.006)." (PMID 35688842, 2022). "In mucosal melanoma, the mutation frequency of BRAF was 12.0% (3/25), which was significantly lower than that in cutaneous melanoma (p = 0.001)." (PMID 35688842, 2022). "Activating mutations of the rapidly accelerated fibrosarcoma B-type (BRAF) gene are found in approximately 60% of cutaneous melanomas, and the therapeutic potential of BRAF inhibition has been harnessed." (PMID 35492830, 2022). "The Cancer Genome Atlas (TCGA) research defined molecular subtypes of cutaneous melanoma on the basis of the presence of specific “driver” gene (BRAF, RAS, and NF1) mutations." (PMID 35688842, 2022). "Compared to the number of BRAF mutations in cutaneous melanoma (32–60%), it is relatively rare in other mucosal melanomas (3–10%)." (PMID 35163401, 2022). "The BRAF mutation seems to be less frequent in vulvar melanoma than in cutaneous melanoma (where it is present in 60–63% of cases))." (PMID 36291906, 2022). "Compared to cutaneous melanoma (CM), which mainly harbors BRAF or NRAS mutations, UM predominantly harbors GNAQ or GNA11 mutations." (PMID 35804863, 2022). "Similar characteristics were observed in the BCH and TCGA-cutaneous melanoma patients, including larger proportions of the male sex, white skin phenotype, metastatic tumor type, UV mutation signature, and BRAF molecular group." (PMID 35840550, 2022). "Mucosal melanomas are rare and only a small portion bear BRAF mutations while cutaneous melanomas have a much higher prevalence and often harbor BRAF mutations." (PMID 34142226, 2022). "Based on the mutational landscape of human cutaneous melanoma and on protein structure data, drugs were designed to specifically block the most-common BRAF mutant, BRAFV600E." (PMID 35234863, 2022). "In the context of BRAF inhibition, our approach identified Rac1/cytoskeletal signaling as an important biological process underlying intrinsic drug resistance in cutaneous melanoma with oncogenic BRAF." (PMID 35581546, 2022). "These analyses revealed that the most frequent gene defect of skin melanoma is the activating mutation of BRAF oncogene in exon 15/codon 600, characterizing almost half of these tumors." (PMID 35628196, 2022). "Approximately 50% of the patients with cutaneous melanoma harbor BRAF mutations, while these are rare in mucosal melanoma." (PMID 34142226, 2022). "Nearly 50% of cutaneous melanoma harbor activating V600E mutations in BRAF, which is considered a prognostic indicator of tumor proliferation, metastasis, recurrence as well as an effective target for SKCM treatment." (PMID 36531226, 2022). "Further analyses suggested that this MCUA association with patient survival is more pronounced in patients with mutations in the BRAF kinase, which is the most commonly altered molecule in cutaneous melanoma patients." (PMID 36156348, 2022). "The most common allelic variants (AV) in cutaneous melanoma tissues include BRAF, neuroblastoma RAS viral oncogene homolog (NRAS), mitogen-activated protein kinase kinase 1 (MAP2K1), and proto-oncogene c-KIT (KIT)." (PMID 35205608, 2022).
cutaneous melanoma (continued). "Nearly 50% of cutaneous melanomas harbor BRAF mutations and can be successfully targeted with BRAF inhibitors in combination with a downstream MEK inhibitor." (PMID 35640549, 2022). "A BRAF gene mutation (variant V600E) is found in roughly 50% of primary skin melanomas; however, the role of this mutation in metastatic melanoma is yet to be determined." (PMID 36291906, 2022). "BRAF V600E SNV has been extensively studied in cutaneous melanoma patients, as the status is associated with clinical outcomes and response to targeted therapies." (PMID 35205608, 2022). "The presence of the activating BRAFV600E mutation in more than 50% of cutaneous melanomas has forced the discovery of BRAF and MEK inhibitors, called targeted therapies." (PMID 35956175, 2022). "Approximately 40 to 60% of cutaneous melanoma patients have BRAF mutations which results in constitutive activation of BRAF, and downstream mitogen activated protein kinase (MAPK) pathway." (PMID 35311078, 2022). "Rare gain-of-function mutations in RAC1 drive drug resistance to targeted BRAF inhibition in cutaneous melanoma." (PMID 36271142, 2022). "This signaling pathway is usually mainly dysregulated by mutations in BRAF or RAS in skin melanomas." (PMID 34222023, 2021). "The identification of BRAF V600 somatic mutations in approximately 50% of cutaneous melanomas led to the development of highly active MAP kinase small molecule inhibitors." (PMID 34069952, 2021). "Although cutaneous malignant melanoma is a molecularly diverse disease, approximately 50% carry activating mutations in the serine/threonine protein kinase BRAF." (PMID 34040017, 2021). "The incidence of BRAF mutation is 35-50% in cutaneous melanoma, while the upstream NRAS mutation frequency is 15-20%." (PMID 34290710, 2021). "BRAF V600E is, globally, the most frequent mutation observed in cutaneous melanoma patients, accounting for 70–88% of all known V600 BRAF mutations." (PMID 33801689, 2021). "Oncogenic BRAF mutations are associated with the efficacy of BRAF inhibitors, and vemurafenib (BRAF V600E) has been demonstrated to extend the survival in clinical trials of patients with BRAF‐mutated skin melanoma." (PMID 34564955, 2021). "BRAF V600K is the second most common mutation (10–20% of all V600 BRAF mutations) in cutaneous melanoma and, as V600E mutation, it consists of an amino acid change, with a valine (V) replaced by a lysine (K)." (PMID 33801689, 2021). "Among them, the most common is the BRAF oncogenic driver V600 mutation, as it is found in 40–50% of cutaneous melanomas." (PMID 34575876, 2021). "Cutaneous melanomas can be classified into four main genetic subtypes: BRAF mutated, RAS mutated, NF1 mutated, and triple-wildtype." (PMID 35008286, 2021). "The previous data showed that about 52% of patients harbored BRAF somatic mutations in cutaneous melanoma and the proportion of BRAF mutations was relatively lower in acral melanoma." (PMID 34221994, 2021). "Since BRAF mutations are present in the majority of cutaneous melanoma patients, ctDNA analysis can be of great value in their context, representing a reliable alternative to the tissue biopsy." (PMID 34575876, 2021). "Some common activating driver mutations in genes identified in cutaneous melanoma, such as mutated BRAF V600E, have less frequently identified in mucosal melanoma." (PMID 34102999, 2021). "Cutaneous melanoma has high incidences of BRAF mutation at V600E (40–60%); thus, BRAF inhibitors vemurafenib and dabrafenib are effective in cutaneous melanoma treatments." (PMID 33477430, 2021). "Forty-six patients were tested for BRAF mutation, out of which 5 (10.8%) were mutated (all positive BRAF cases were cutaneous melanomas), 1 (2.1%) was uninterpretable, and 40 (86.9%) were wild type." (PMID 34568037, 2021). "Acral melanoma is the most common subtype in the Chinese population, with lower incidence of BRAF mutations than cutaneous melanoma." (PMID 34504796, 2021).
cutaneous melanoma (continued). "CM shares similarities with both cutaneous melanoma and mucosal melanoma, including their infiltrative nature, their lymphatic and hematogenous spread and the presence of BRAF, NRAS, NF1 and Kit mutations." (PMID 34830847, 2021). "Like cutaneous melanomas, it has been proposed to classify CMs according to their mutational status, resulting in groups of BRAF-mutated, NRAS-mutated, NF1-mutated and triple-wild type (WT) melanomas." (PMID 34830847, 2021). "Analysis of TCGA PanCancer Atlas (skin cutaneous melanoma) showed that patients with a BRAF mutation and high levels of IGF1R and INSR had a worse overall survival." (PMID 34831014, 2021). "Cutaneous melanoma is a particularly suitable model since BRAF or NRAS hotspot mutations are found in 60% to 70% of patients and are already routinely investigated for any metastatic cutaneous melanoma." (PMID 33920470, 2021). "Oncogene mutations commonly found in cutaneous melanoma in humans, like BRAF and NRAS, are uncommon in mucosal melanoma in either humans or dogs, while activation of the ERK and AKT signaling pathways are common in both species." (PMID 35053051, 2021). "Our analysis revealed particularly striking similarities between UVR-exposed mucosal melanomas and UVR-driven common cutaneous melanomas, as both presented high mutation burdens and abundant mutations that activate the BRAF–ERK pathway." (PMID 33431815, 2021). "BRAF V600E/K mutated lung adenocarcinoma and cutaneous melanoma both were predicted to be more sensitive to Trametinib and Dabrafenib (all with p < 0.001)." (PMID 34548481, 2021). "CoM on the other hand resembles cutaneous melanoma and has driver mutations in BRAF, NRAS, Kit, TERT, or NF1.20–25 Despite their different backgrounds, UM and CoM share the need for the development of new and effective therapies." (PMID 33798262, 2021). "Concerning prognosis, BRAF V600 mutations are statistically significantly associated with reduced OS in cutaneous melanoma patients." (PMID 33801689, 2021). "the BRAF subtype which accounts for the majority of cutaneous melanomas (~52%) and it is characterized by the presence of a mutation on the BRAF gene; ii." (PMID 34123788, 2021). "BRAF was also enriched by skin cancer cell lines which was unsurprising because BRAF mutations occur in nearly 70% of cutaneous melanomas." (PMID 33842927, 2021). "In cutaneous epidermal melanocytes, the BRAF p.V600E mutation – an established oncogenic driver of cutaneous melanoma – is considered sufficient to initiate nevus formation." (PMID 33588787, 2021). "Mutations in cutaneous melanoma were primarily observed in v-Raf murine sarcoma viral oncogene homolog B (BRAF)." (PMID 32367253, 2020). "BRAF is the most common mutated gene in cutaneous melanoma, ranging from 40–60% of cases, and leading to uncontrolled activation of the mitogen-activated protein kinases (MAPK) pathway." (PMID 33233603, 2020). "About 40 to 60% of skin melanomas carry BRAF gene mutations (V600E), which causes downstream signals continuous activation through the MAPK pathway." (PMID 32216825, 2020). "Despite this good purpose, to date, only BRAF mutations have FDA approved therapies in advanced cutaneous melanoma, whereas KIT mutations have the tyrosine kinase inhibitors Imatinib as off-label prescription." (PMID 32695793, 2020).
cutaneous melanoma (continued). "BRAF is one of the most common mutated kinases detected in human cancer, particularly in cases of primary cutaneous melanomas (PCM)." (PMID 32754440, 2020). "An activating mutation in BRAF, with a constitutive activation of the kinase, is found in about 50% of cutaneous melanomas, mostly the BRAF V600E." (PMID 32695793, 2020). "Another difference with cutaneous melanoma is that the targetable mutations in BRAF and NRAS genes are less prevalent in mucosal melanoma (only 3–15%)." (PMID 33585548, 2020). "While BRAF mutations are the most prevalent in cutaneous melanoma, NRAS mutations display more aggressive phenotypes with increased mitotic rate, thicker primary tumors, and poorer prognosis." (PMID 32517051, 2020). "In a study on the development of cutaneous melanoma, a BRAF mutation was introduced in three different types of mice: red mice with an abundance of pheomelanin, albino mice with no melanin and black mice with an abundance of eumelanin." (PMID 32998469, 2020). "Most notably, mutations affecting BRAF are found in more than half of patients diagnosed with cutaneous melanoma." (PMID 32645969, 2020). "In particular, BRAF is mutated in about 50% of cutaneous melanomas, and among these, in 80–90% of the cases, the missense activating mutation V600E is present." (PMID 33003469, 2020). "Combinations of BRAFi and MEKi were applied in 16.3% of cases, a standard TT-treatment for BRAF-mutated cutaneous melanoma according to ESMO guidelines." (PMID 32487100, 2020). "The major driver of skin melanoma is the mutant BRAF in almost half of the cases followed by NRAS mutation as the second most frequent one." (PMID 31848942, 2020). "We present a 59-year-old woman, who was treated with pembrolizumab for a relapsed BRAF V600E mutated cutaneous malignant melanoma." (PMID 32150095, 2020). "The most relevant mutated gene is BRAF, which is mutated in about 50% to 70% of cutaneous melanomas, and the most common genetic change is a glutamic acid for valine substitution at position 600 (V600E)." (PMID 36046072, 2020). "For instance, The Cancer Genome Atlas (TCGA) defined three genomic subtypes of cutaneous melanoma based on the mutation status of BRAF, NRAS, NF1, and a fourth subgroup termed triple wild-type." (PMID 32517051, 2020). "Based on these results, ddPCR should be the primary method of detecting and monitoring BRAF V600E-mutated cutaneous melanomas as methods of screening thanks to the higher sensitivity and lower LOD of mutant allele." (PMID 32695793, 2020). "BRAF V600E mutations are found in approximately half of all cutaneous melanomas, and the use of BRAF inhibitors in these patients has been shown to improve survival." (PMID 32087721, 2020). "Oncogenic BRAF mutation has been shown to be a factor associated with worse prognosis in cutaneous melanoma." (PMID 32143442, 2020). "BRAF mutations account for approximately 52% of cutaneous melanoma mutations, compared to only 6% in mucosal melanoma." (PMID 32517051, 2020). "We divide cutaneous melanoma into four subtypes (BRAF-mutant, NF1-deficient, NRAS-mutant and triple wild-type)." (PMID 33585219, 2020). "UMs most often have a GNAQ or GNA11 mutation, while cutaneous melanomas usually have a BRAF, NRAS, KIT or NF1 mutation." (PMID 32998469, 2020). "Further analysis of the 124 BRAF-wild type skin melanomas, we found the NRAS mutation frequency to be 20% (45/227)." (PMID 31848942, 2020). "Although modern targeted therapies such as BRAF inhibitors are showing some promise, mutations in BRAF are observed in approximately 50% of skin melanomas and are linked to acquired resistance, which occurs in half of diagnosed patients." (PMID 33171765, 2020). "of cutaneous melanoma cohort consecutively diagnostically tested between 2014 and 2018, we found that the BRAF mutation frequency in skin melanoma in Hungary is 45.4% (103/227) confirming data from other ethnicities and geographical regions." (PMID 31848942, 2020).
cutaneous melanoma (continued). "BRAF mutations occur in more than 50% of cutaneous melanomas, with BRAF V600E being the most common; this mutation results in constitutive monomeric activation of BRAF kinase activity." (PMID 33203961, 2020). "Mutations of BRAF are the most common mutations leading to overactivation of the MAPK pathway, and BRAF-activating mutations are found in more than half of cutaneous melanomas." (PMID 32645969, 2020). "BRAF mutations have been detected in up to 50% of primary and metastatic conjunctival melanomas as in cutaneous melanoma." (PMID 31683701, 2019). "BRAF mutations occur in more than 50% of cutaneous melanomas, and BRAF V600E occurs most frequently, which confers constitutive monomeric activation of BRAF kinase activity." (PMID 31058079, 2019). "In our study, a signifi- cant association between the immunohistochemical expression of BRAF V600E and malignant skin melanomas was noted." (PMID 31531096, 2019). "We compared those data with BRAF mutations in cutaneous melanomas, hematopoietic and lymphoid tissue malignancies, thyroid cancers, and lung adenocarcinoma from The Catalog of Somatic Mutations in Cancer." (PMID 31398831, 2019). "Examining the preferred single-base substitutions collated from NRAS and BRAF in mucosal melanoma revealed a different mutation profile than cutaneous melanoma, suggesting different etiologies for both malignancies." (PMID 31398831, 2019). "Cutaneous melanoma can be divided into molecular subgroups (BRAF mutated, NRAS mutated, NF1 mutated, triple wild-type) and show the typical ultra violet (UV) signature (C > T transition)." (PMID 31500314, 2019). "For example, cutaneous melanomas closely associated with ultraviolet exposure are characterized by activating mutations of BRAF and NRAS, with loss of the PTEN expression." (PMID 31581559, 2019). "We also demonstrated that mutations in NRAS and BRAF in mucosal melanoma are different from the ones found in cutaneous melanoma, suggesting the existence of genotoxic agents in mucosal melanoma that remain to be identified." (PMID 31398831, 2019). "In the majority of cases UV-induced human skin melanoma is characterized by founder somatic mutations of two oncogenes, BRAF and NRAS." (PMID 31391014, 2019). "The incidence of BRAF mutation was similar in cutaneous melanomas with the primary tumor located within or outside the head, neck and upper back areas (45% vs. 47%)." (PMID 31277584, 2019). "We validated previous reports that the commonly known mutations in cutaneous melanoma, including BRAF, NRAS, NF1, GNAQ and GNA11, were rarely mutated in mucosal melanomas." (PMID 30847022, 2019). "This is interesting because, although BRAF mutations are rare in mucosal melanoma, they are characterized by a higher prevalence of non-V600 mutations than in cutaneous melanoma." (PMID 31398831, 2019). "RAC1 P29 is the third most commonly mutated codon in human cutaneous melanoma, after BRAF V600 and NRAS Q61." (PMID 31257073, 2019). "BRAF-mutated kinase is the driver mutation found in approximately 30.4–66.0% of cutaneous melanomas." (PMID 31514399, 2019). "Further, there is a high frequency of BRAF gene-mutations in cutaneous melanomas as compared with uveal or mucosal melanomas, suggesting a link between BRAF mutations and UV exposure." (PMID 31552252, 2019). "c-KIT mutations have been detected in almost 2–7% of conjunctival melanomas and they are mutually exclusive with NRAS and BRAF mutations, as in cutaneous melanoma." (PMID 31683701, 2019). "Primary cutaneous malignant melanoma is a cancer of the pigment cells of the skin, some of which are accompanied by BRAF mutation." (PMID 30925905, 2019). "About 50% of cutaneous melanomas carry a mutation in BRAF gene, which is in approximately 50% cases represented by V600E substitution, followed by V600K (10–15%) and several less frequent mutations." (PMID 31717496, 2019).